EPG5 (ectopic P-granules 5 autophagy tethering factor)
Diseases named in the same sentence as EPG5 in open-access papers (continued):
Sharing a sentence is not in itself a finding about the gene and the disease.
EPG5 also shares sentences with these, for which no sentence is quoted: developmental delay (4 papers); Failure to thrive (4); breast carcinoma (3); cancer (3); lysosomal storage disorders (3); Chediak-Higashi syndrome (2); vitiligo (2); albinism (1); Arrhythmogenic right ventricular dysplasia (1); centronuclear myopathies (1); cerebellar ataxia (1); chronic pancreatitis (1); cognitive decline (1); cystinosis (1); Dystonia (1); epileptic encephalopathies (1); gastroesophageal reflux disease (1); Gaucher disease (1); generalized dystonia (1); glioblastoma (1); glioma (1); glycogen storage disorders (1); hearing loss (1); Hirschsprung disease (1); infantile epileptic encephalopathy (1); Intellectual disability (1); Lafora body disease (1); Lung (1); Marinesco-Sjogren syndrome (1); mitochondrial disease (1).
A further 15 diseases each share a sentence with EPG5 in 1 paper.